PGA4 (pepsinogen A4)
Description:
Shows particularly broad specificity; although bonds involving phenylalanine and leucine are preferred, many others are also cleaved to some extent.
Tractability: Small molecule: a structure with a bound ligand is known; it has a high-quality binding pocket; it belongs to a druggable protein family. Antibody: UniProt places it where antibodies can reach, with medium confidence; UniProt predicts a signal peptide or a membrane-spanning region; its Gene Ontology location is reachable by antibodies, with medium confidence.
Gene: Protein-coding gene on chromosome 11 (61,222,347 to 61,231,694, forward strand). Ensembl gene ENSG00000229183.
Subcellular location: Secreted
Pathways (Reactome):
Metabolism of proteins: Surfactant metabolism
Gene Ontology:
Molecular function: protein binding; aspartic-type endopeptidase activity
Biological process: proteolysis
Cellular component: extracellular exosome; multivesicular body lumen; extracellular region
Homologues: Orthologues: macaque PGA4 (94% identical), pig PGA5 (82% identical), dog PGA (82% identical), tropical clawed frog pga4 (68% identical), Drosophila melanogaster Bace (43% identical), Drosophila melanogaster CG17134 (41% identical), Drosophila melanogaster CG6508 (39% identical), Drosophila melanogaster CG33128 (39% identical), Caenorhabditis elegans asp-1 (34% identical), Caenorhabditis elegans asp-16 (34% identical), Caenorhabditis elegans asp-17 (33% identical), Caenorhabditis elegans asp-18 (32% identical), and 6 more. Paralogues in human: PGA3 (99% identical), PGA5 (99% identical), CTSE (54% identical), PGC (50% identical), CTSD (45% identical), NAPSA (41% identical), REN (35% identical), BACE1 (30% identical), BACE2 (30% identical).
Diseases named in the same sentence as PGA4 in open-access papers:
PGA4 is named in the same sentence as 18 diseases in open-access papers, as found by Europe PMC text mining. Sharing a sentence is not in itself a finding about the gene and the disease. The quoted sentences say what the papers report.
Barrett esophagus (2 papers, 2016 to 2020). Esophageal lesion lined with columnar metaplastic epithelium which is flat or villiform. "PGA3, PGA4, and PGA5 encode pepsinogen A (PGA), and the differential expression of PGA3, PGA4, and PGA5 is related to the pre-neoplastic nature in patients with Barrett’s esophagus." (PMID 27855662, 2016).
gastric adenocarcinoma (2 papers, 2020 to 2025). "Conversely, the most significantly downregulated genes included LIPF (gastric lipase), PGA4 and PGA3 (pepsinogens), reflecting the characteristic loss of gastric digestive enzyme production in gastric adenocarcinoma." (PMID 40725485, 2025). "The expression of PGA3 and PGA4 increased in kidney renal clear cell carcinoma but decreased in thyroid carcinoma and stomach adenocarcinoma." (PMID 33067881, 2020).
gastric cancer (2 papers, 2011 to 2020). A primary or metastatic malignant neoplasm involving the stomach. "PGA3 and PGA5 are mainly expressed in ovarian cancer and lung cancer, while PGA4 is mainly expressed in lung cancer and gastric cancer cell lines." (PMID 33067881, 2020).
bladder urothelial carcinoma (1 paper, 2020). "PGA3, PGA4, and PGA5 showed more copy number amplification in lung adenocarcinoma, esophageal carcinoma, kidney chromophobe, and copy number reduction in bladder urothelial carcinoma, lung squamous cell carcinoma, rectum adenocarcinoma, and cholangiocarcinoma." (PMID 33067881, 2020).
cancer (3 papers, 2011 to 2023). A tumor composed of atypical neoplastic, often pleomorphic cells that invade other tissues. "The mutation rates of PGA3, PGA4, and PGA5 in all cancer lines were low and less than 2%." (PMID 33067881, 2020). "Using the count data of 33 human tumors covered by TCGA, we analyzed the differential expression of PG family genes including PGC, PGA3, PGA4, and PGA5 in different cancers at the overall level based on continuous variable analysis." (PMID 33067881, 2020). "PGA3, PGA4, and PGA5 are mainly involved in K‐RAS signaling pathway, bile acid metabolism, mitotic G2 M phase, and other cancer‐related pathways." (PMID 33067881, 2020). "PGA3, PGA4, and PGA5 were expressed in most normal tissues, but decreased in cancer tissues." (PMID 33067881, 2020). "The data of 21 kinds of cancers from The Protein Atlas showed that the expression of PGA3, PGA4, and PGA5 could not be detected in any cancer tissues." (PMID 33067881, 2020).
tumor (3 papers, 2013 to 2024). "Both these genes were oncogenes, and downregulated genes such as ATP4A, ATP4B, PGA3, PGA4, and PGA5 were reported tumor suppressors in GC." (PMID 39283078, 2024).
PGA4 also shares sentences with these, for which no sentence is quoted: cholangiocarcinoma (1 paper); esophageal carcinoma (1); Follicular Cyst (1); lung adenocarcinoma (1); lung carcinoma (1); lung squamous cell carcinoma (1); mastitis (1); multiple sclerosis (1); myasthenia gravis (1); ovarian carcinoma (1); rectum adenocarcinoma (1); thyroid carcinoma (1).